NPIPB14P (nuclear pore complex interacting protein family member B14, pseudogene)
Gene: Transcribed unprocessed pseudogene on chromosome 16 (69,976,388 to 69,996,188, reverse strand). Ensembl gene ENSG00000226232.
Diseases named in the same sentence as NPIPB14P in open-access papers:
NPIPB14P is named in the same sentence as 1 disease in open-access papers, as found by Europe PMC text mining. Sharing a sentence is not in itself a finding about the gene and the disease.
NPIPB14P shares sentences with these, for which no sentence is quoted: thyroid abnormality (1 paper).